FTO (FTO alpha-ketoglutarate dependent dioxygenase)
Diseases named in the same sentence as FTO in open-access papers (continued):
Sharing a sentence is not in itself a finding about the gene and the disease.
Obesity (continued). "FTO ensures the balance of m6A modification in the transcriptome and is widely recognized for its role in human obesity and adipogenesis." (PMID 35721711, 2022). "Alpha-ketoglutarate-dependent dioxygenase (FTO) is the gene with the most significant impact on obesity." (PMID 36532520, 2022). "Since it was discovered as an obesity-related gene, most of the existing studies have focused on the roles of FTO in obesity." (PMID 35528183, 2022). "Obesity-related traits correlating to the FTO loci can be observed in Western European, Hispanic/Latino, Asian and Pima Indian populations." (PMID 36278751, 2022). "The association between FTO and ADRB2 genetic polymorphisms and obesity phenotypes appears to be modified by diet composition." (PMID 35268025, 2022). "- Anti-obesity [↓body weight (10 g/kg bw)] and promoted methylation of CpG island in the FTO promoter in HFD-mice (2, 5, 10 g/kg bw, p.o., 4 weeks). - FTO expression in high dose group (10 g/kg bw) were significantly higher than control." (PMID 35769384, 2022). "Statistical and biological interactions with MD modulate the effects of FTO and MC4R polymorphisms on obesity." (PMID 35327974, 2022). "We found an interaction between FTO rs9939609, rs8050136, rs1421085 and rs1121980 polymorphism carriers and SSB on obesity risk in women." (PMID 36235854, 2022). "Yet, none has been critically evaluated in terms of their in-vivo efficacy in the context of FTO pathological implications like obesity or cancers." (PMID 35409166, 2022). "Several studies have shown that abnormal variations in FTO expression are closely related to obesity." (PMID 36536469, 2022). "The fat mass and obesity-related (FTO) gene has been reported to be involved in common obesity and body mass index." (PMID 35706030, 2022). "Early GWAS identified an extended haplotype block of 89 common variants, located in introns 1 and 2 of a gene named Fat Mass And Obesity Associated (FTO), as a risk locus for obesity (as measured by high body mass index [BMI])." (PMID 37034418, 2022). "FTO-dependent m6A demethylation contributes to human obesity and regulates energy balance, which is critical for its biological role in the cardiovascular system." (PMID 36354766, 2022). "FTO (FTO alpha-ketoglutarate dependent dioxygenase; HGNC:24678) was the first gene associated with obesity identified by GWAS." (PMID 36339410, 2022). "We also identified one locus on chromosome 16q12.2 (rs56094641, p = 1.3 × 10−14) harbouring FTO, best known genes influencing both nutrition and obesity." (PMID 36297114, 2022). "In case of the three genetic variants of CEPT, FTO and LEP genes, MAFs were higher in lean-normal body mass and showed obesity protective association." (PMID 36126070, 2022). "FTO is related to human obesity and mental development and was the first m6A mRNA demethylase identified to convert mRNA m6A to adenosine in mRNA." (PMID 36120301, 2022). "Despite the advances in genomic research, the mechanistic action in which FTO SNPs contribute to obesity is not fully understood." (PMID 36278751, 2022). "The most significant locus (index SNP rs9937053, pmeta = 6.72 × 10− 81) was mapped to FTO, the first gene contributing to common forms of human obesity." (PMID 35250867, 2022). "The study reported herein revealed that SMF and SAF possess anti-obesity properties via the modulation of mRNA levels of the FTO gene." (PMID 35800074, 2022). "This study demonstrated that a green cardamom intervention improved anthropometric indices, glycemic indices, and sexual hormones, as well as the expression level of obesity and diabetes genes FTO, CPT1A, LEPR, LAMIN, and PPAR-γ genes in PCOS women." (PMID 36522620, 2022). "In past decades, a large number of GWASs have identified hundreds of genes that are associated with obesity, including FTO, MC4R and POMC, and a few of them have been established as obesity genes before." (PMID 36676030, 2022).
Obesity (continued). "Since the discovery that its overexpression links to the development of obesity and cancer, FTO was the target of screening campaigns and structure-based drug design efforts." (PMID 35398093, 2022). "Previously, it has been reported that the genetic variants in ADIPOQ, CETP, FTO, LEP, and LEPR genes are strongly correlated with obesity and associated metabolic complications in different ethnicities of the world." (PMID 36126070, 2022). "Considering the most well-known associations between obesity and strokes, we aimed to assess the potential genetic roles of the MC4R and the FTO in populations susceptible to stroke." (PMID 36530622, 2022). "Thus, we posit that it might be possible that the BMI decreasing allele of rs6567160 near MC4R, contributing to its expression levels, has a significant mitigating effect on obesity in conjunction with the homozygous decreasing allele or heterozygous stature of the FTO SNP." (PMID 35508500, 2022). "Studies linking FTO expression with white adipose tissue browning represent novel avenues for better obesity management in the future." (PMID 35409166, 2022). "While on the other end, in EA children we saw an increase in DNA methylation of both NRF1 and FTO genes as their BMI z-score increased, implying that in the EA population, the methylation status depends more on their obesity status." (PMID 36360268, 2022). "In the obesity group, high FTO level is positively correlated with Body Mass Index (BMI) and body fat." (PMID 36157445, 2022). "Population studies have shown that FTO gene has SNP loci regulating fat metabolism in human body, leading to the occurrence of obesity." (PMID 35651949, 2022). "Specifically, the most pleiotropic SNP in the PGS, rs1421085, is mapped to the FTO gene, which is well known for its effect on obesity and anthropometric traits, type 2 diabetes, alcohol consumption, among others." (PMID 36579561, 2022). "Both FTO and MC4R gene variants are associated with obesity in PCOS while observational evidence indicates a direct role of the interaction between FTO and MC4R polymorphisms in the development of PCOS." (PMID 35679284, 2022). "Above all, characterizing the role of the FTO gene has greatly contributed to clarifying the mechanism of m6A in obesity." (PMID 36578520, 2022). "Overall, we report six genetic variants of ADIPOQ, FTO and LEPR genes as obesity-risk markers and a CETP gene variant as lean mass/obesity protective marker in studied Pakistani cohort." (PMID 36126070, 2022). "Their study provided mechanistic insights relating FTO upregulation with obesity; where it regulates early adipogenesis during the mitotic clonal expansion (MCE) phase." (PMID 35409166, 2022). "The polymorphisms in the FTO and the MC4R were linked to overweight or obesity in children and adolescents." (PMID 36530622, 2022). "Genome-wide association studies and multiple experimental studies have identified FTO as a genetic factor for obesity." (PMID 36461116, 2022). "Evaluated genotypes also included those relating to cardiovascular health (ACE), obesity and metabolism-related genotypes (FTO, UCP1, MC4R, and ADIPOQ), sweet taste perception (Tas1R2 and KCTD10), and endurance (GDF5)." (PMID 36235756, 2022). "In fact, FTO is an important gene in obesity pathogenesis due to its ability to modulate food intake and satiety perception; however, these modulations are often linked to a genetic polymorphism rather than to gene expression." (PMID 36386923, 2022). "Treatment with orlistat, SMF, SAF, or SMF + SAF for 3 weeks after induction of obesity significantly (****p < 0.0001) downregulated the mRNA levels of the FTO gene in all treatment groups in a dose-dependent manner when compared with the untreated group." (PMID 35800074, 2022).
Obesity (continued). "Although the analysis of individual SNPs showed only one association between harboring the specific FTO genotype and FMI, the gene–gene interaction analysis revealed numerous links between the genotypes of studied genes and obesity-related traits." (PMID 35627568, 2022). "This is supported by other studies, whereby variations of the FTO genes have been reported as contributors to childhood and adult obesity, as well as T2DM, both being features of the MetS." (PMID 35054972, 2022). "The FTO gene which is highly dysregulated and known to be involved in various types of cancer and obesity has been recently identified." (PMID 35923209, 2022). "FTO, a gene closely related to obesity, is an active regulator of energy homeostasis that regulates the m6A levels in human RNA sequences via lipid metabolism." (PMID 35406663, 2022). "Among the measurement of the obesity and diabetes genes, the expression level of FTO, CPT1A, LEPR, and LAMIN were significantly downregulated in the intervention group after intervention with green cardamom (P < 0.001)." (PMID 36522620, 2022). "They analyzed the five obesity-associated genetic variants (MC4R rs17782313, BDNF rs6265, FTO rs1421085, TMEM18 rs7561317, and NEGR1 rs2815752)." (PMID 35627568, 2022). "Here we review the molecular bases of m6A in tumorigenesis and adipogenesis while highlighting the controversial role of FTO in obesity." (PMID 35409166, 2022). "Initially, FTO was reported to link to obesity in the genome-wide search for type 2 diabetes-sensitive genes." (PMID 35628623, 2022). "FTO rs9939609 and MC4R rs17782313 polymorphisms have been associated with overweight and obesity in children." (PMID 36499740, 2022). "Several studies have shown a significant association between the FTO rs9930506 and MC4R rs17782313 polymorphisms and obesity in children." (PMID 36499740, 2022). "Among obesity-related genes, the FTO gene has one of the strongest links with obesity in the human population." (PMID 37990728, 2022). "All in all, further insight is necessary to elaborate on the FTO gene’s role in the mechanism of obesity pathogenesis and metabolic disturbances among psoriatic patients." (PMID 35806402, 2022). "For obesity (ADRB3 and FTO genes) the lowest average risk score was calculated for the Parakanã (0.188) and the highest for the Araweté group (0.413)." (PMID 35560161, 2022). "Here we review studies from both groups and support the fact that FTO does directly modulate obesity on the m6A level." (PMID 35409166, 2022). "Here, we showed that high fat mass and obesity-associated gene (FTO) expression was associated with a poor prognosis in PDAC patients and that suppression of FTO expression inhibited cell proliferation." (PMID 35422475, 2022). "FTO regulates obesity and adipogenesis through autophagy and provides energy for tumor survival through lipid metabolism." (PMID 35794625, 2022). "Although rare monogenic variants associated with obesity result from highly infrequent single-gene mutations (such as LEP, POMC), some of them were also associated with polygenic obesity (e.g., MC4R, FTO)." (PMID 35806402, 2022). "Endothelial FTO knockout protected mice from obesity-induced insulin resistance, hyperglycemia, and hypertension in endothelial cells and skeletal muscle in obese conditions." (PMID 35628623, 2022). "Development of FTO-specific inhibitors from natural phytochemicals is a promising strategy to avoid the side effects of synthetic drugs for treatment of obesity and other chronic diseases." (PMID 35769384, 2022). "A number of studies have reported the use of biochemical inhibitors of FTO, considering its pathological implications in obesity and cancers for instance." (PMID 35409166, 2022). "Treatment with orlistat, SMF, SAF, or SMF + SAF for 3 weeks after induction of obesity significantly downregulated the mRNA levels of the FTO gene in all treatment groups in a dose-dependent manner when compared with the untreated control (group 2)." (PMID 35800074, 2022).
Obesity (continued). "Metformin increases m6A methylation levels of CCND1 and CDK2 by inhibiting FTO expression, thereby inhibiting adipogenesis and combating obesity." (PMID 36461116, 2022). "On the other hand, FTO, as an obesity-related gene, can also inhibit the occurrence of depression through reducing the BMI." (PMID 35528183, 2022). "FTO is also known for its close correlation with weight gain and obesity in children and adults previously." (PMID 35721711, 2022). "Our results showed that the association signal was fully attenuated after BMI adjustment, insinuating the possibility that the FTO gene exerts its effect on OA through obesity in the Caucasian population." (PMID 36213660, 2022). "For gene FTO, despite a large number of studies that have confirmed its contribution to adult obesity, childhood obesity, and obesity-related traits, its role in PCOS remains controversial." (PMID 35144605, 2022). "For example, the expression of the obesity-related gene FTO (an RNA demethylase) is downregulated in the hippocampus of in a mouse model of depression, whereas overexpression of FTO has antidepressant effects." (PMID 35480327, 2022). "To further assess the potential role of CTNNB1 in FTO-regulated chicken obesity development, we examined the expression of CTNNB1 in FTO-overexpressed and knockdown chicken preadipocytes." (PMID 36461116, 2022). "Since the initial identification of FTO as an m6A demethylase, a number of recent studies began to unravel a connection between FTO-dependent m6A demethylation and obesity." (PMID 35409166, 2022). "Genomic studies have shown that the expression of the fat mass obesity (FTO) gene was highly altered and identified as one of the key biomarkers for obesity." (PMID 35923209, 2022). "Among them, FTO was first identified as a gene related to obesity and energy metabolism and was then recognized as an RNA m6A demethylase." (PMID 35712246, 2022). "Of the identified genes in our study, FTO, GNPDA2, MC4R, MTCH2, NEGR1, SH2B1, TMEM18 are unequivocally regarded as obesity genes associated with PCOS, as supported by contemporary evidence." (PMID 35679284, 2022). "Obesity and metabolism-related genotypes were also assessed by 10 studies, including FTO, UCP1, MC4R, and ADIPOQ." (PMID 36235756, 2022). "The Food4Me study showed that PA attenuated the effect of the FTO genotype on obesity traits in European adults." (PMID 35811975, 2022). "Obesity is known to be correlated with PCOS causing ovulatory dysfunction and hormone imbalances.Moreover, fat mass and the obesity gene (FTO) were linked with obesity and PCOS." (PMID 35655906, 2021). "In conclusion, in the present study, we evaluated obesity-associated gene polymorphisms, namely, ADIPOQ rs1501299 and rs2241766, FTO rs1477196, rs7206790, rs8047395, and rs9939609 for the first time together in Turkish postmenopausal ER (+) BC patients." (PMID 34345232, 2021). "The FTO protein, a member of the ALKBH family, has been found to be associated with obesity and other diseases of affluence like type 2 diabetes and cancer." (PMID 33925955, 2021). "We show that candidate SNPs in the FTO and TUB genes are associated with obesity in African Americans and Hispanic/Latinos individuals respectively." (PMID 33983957, 2021). "Obesity-associated gene polymorphisms ADIPOQ rs1501299 and rs2241766, and FTO rs1477196, rs7206790, rs8047395, and rs9939609 were studied in 101 Turkish postmenopausal estrogen receptor-positive BC patients and 100 healthy control individuals." (PMID 34345232, 2021). "FTO (alias ALKBH9), famous as an obesity-related gene, is a member of the α-ketoglutarate-dependent dioxygenase protein family and was the first m6A demethylase to be identified." (PMID 33926508, 2021). "As one of the crucial enzymes of m6A modification, FTO played an indispensable role in obesity and cancer." (PMID 34725345, 2021).
Obesity (continued). "For both genes, the FTO and FGF21, the prevalence of obesity was highest for the homozygous risk alleles, except for the FGF21 rs838145, where the highest obesity prevalence was observed among the heterozygous A/G." (PMID 34095191, 2021). "Related to this, as far as we know our study population is still the largest one of individuals with uniform severe obesity in whom glucose metabolism has been extensively investigated with a focus on FTO genetics." (PMID 33684170, 2021). "FTO was first identified as a gene related to obesity and energy metabolism and was then identified as the RNA m6A demethylase." (PMID 34218271, 2021). "The FTO is the best-known obesity-related gene which can exert its effects through several mechanisms such as impacts on eating behaviors, energy homeostasis, and body fat storage." (PMID 34399781, 2021). "An excessive expression of FTO increases food intake, leading to a positive energy balance and obesity." (PMID 34650918, 2021). "Sedentary behaviors increased the effects of SNPs on BMI and WC, and simultaneously increased the effects of FTO rs9939609 and FTO rs8050136 on obesity and central obesity." (PMID 33668547, 2021). "Further, the rs1558902 FTO site is protective from obesity, with prominent effects on a high-protein diet, an example of a gene-dietary interaction." (PMID 34844590, 2021). "The British Biobank’s research showed that a low socioeconomic status would aggravate the effect of the FTO gene on obesity." (PMID 33668547, 2021). "In particular, it is unclear if and in what way does the newly discovered substrate of FTO, m6Am, regulates obesity." (PMID 34893620, 2021). "AMPK regulates skeletal muscle lipid accumulation through fat quality and obesity-related protein by FTO-dependent m6A demethylation." (PMID 33994853, 2021). "We showed that rs8050136 (in FTO) in AAs and rs2272383 (in TUB) in H/Ls were associated with obesity." (PMID 33983957, 2021). "Fat mass and obesity-associated protein (FTO) was the first discovered m6A eraser which regulates cellular energy homeostasis and is associated with obesity." (PMID 33814008, 2021). "Since the first discovery of FTO in mouse in 1999, the functional roles of FTO have been extensively investigated in obesity, Alzheimer's disease, and recently in cancers." (PMID 34378866, 2021). "A study of 18 volunteers who agreed to have a genetic test for the FTO gene related to obesity believed that knowing their result would motivate them to try to control their weight in the future." (PMID 34748551, 2021). "The SNP rs9939609 (also commonly referred to by the nearby gene name, FTO) is of particular interest for studies of obesity." (PMID 34662357, 2021). "In our study, after adjusting the main variable for age and sex of children, and for any interaction existing between covariates, we only obtained a result close to statistical significance for FTO gene methylation and obesity." (PMID 34063412, 2021). "FTO is reported to and positively related to obesity and T2D, and FTO levels were significantly increased in NAFLD group 106,107." (PMID 33390849, 2021). "As the first identified RNA demethylase, FTO was closely related with increased body mass and obesity, and reported to regulate dopaminergic signaling in adipogenesis and leukemogenesis." (PMID 34496349, 2021). "The association of FTO rs9939609 variants with the CRC in Iranian evident in this study further suggested the shared role of energy metabolism and obesity pathways in colorectal cancer." (PMID 34650918, 2021). "FTO is an essential regulator in the development of obesity-induced metabolic and vascular changes, which is independent of its known function in regulation of obesity." (PMID 33910581, 2021). "The prevalent m6Am mRNA cap modification was recently identified as a valid target for removal by the human obesity gene FTO along with the previously established m6A mRNA modification." (PMID 34893620, 2021).